GCG (glucagon)
Diseases named in the same sentence as GCG in open-access papers (continued):
Sharing a sentence is not in itself a finding about the gene and the disease.
myeloid leukaemia (1 paper, 2021). "Functional annotation analyses indicated that these DEGs were mostly significantly enriched in insulin signalling, myeloid leukaemia, and glucagon signalling pathways." (PMID 33596828, 2021).
neonatal diabetes mellitus (1 paper, 2016). Neonatal diabetes mellitus presents as hyperglycemia, failure to thrive and, in some cases, dehydration and ketoacidosis which may be severe with coma, in a child within the first months of life. "We previously reported that patients with permanent neonatal diabetes mellitus (PNDM) due to proteotoxic MIDY mutations have fasting hyperglucagonemia, suggesting loss of insulin- mediated intra-islet suppression of glucagon production." (PMID 28702245, 2016).
Neoplasm of the pancreas (1 paper, 2024). A tumor (abnormal growth of tissue) of the pancreas. "This study analyzed a cohort of six patients with clinically functional neuroendocrine glucagon-producing neoplasms of the pancreas." (PMID 39331358, 2024).
ovarian tumors (1 paper, 2025). "Prostate and ovarian tumors also exhibited a moderate increase in GCG expression compared to their normal counterparts, but the expression levels were significantly lower than those observed in the pancreas." (PMID 39777709, 2025).
Pancreatic cysts (1 paper, 2026). A cyst of the pancreas that possess a lining of mucous epithelium. "In contrast, the heterozygous brother and two sons showed mild biochemical changes, such as elevated glucagon levels and small pancreatic cysts, without overt disease." (PMID 41649336, 2026).
Pancreatic Glucagonoma (1 paper, 2010). A usually malignant, glucagon-producing neuroendocrine tumor arising from the pancreatic alpha cells. "This case report demonstrates that the differential immunohistochemical reactivities of Siemens' Double Antibody Glucagon compared to DakoCytomation's Polyclonal Rabbit Anti-Human Glucagon allow for pathologic distinction of enteral versus pancreatic glucagonoma." (PMID 20550685, 2010).
pancreatic NEC (1 paper, 2024). "Six of seven pancreatic NEC-like G3NETs corresponded to the PanNET subtypes A1 or A2 (characterized by predominantly glucagon expression) and one to subtype B (characterized by insulin expression)." (PMID 39382626, 2024).
pancreatic NEN (1 paper, 2022). "With similar infrequency, glucagonomas (pancreatic NEN with hypersecretion of glucagon) have very few documented cases in the literature in pediatric and young adult patients." (PMID 36291833, 2022).
Paralytic ileus (1 paper, 2022). "It will be worthwhile to analyze the rates of glucagon usage and their effects on outcomes for patients with paralytic ileus." (PMID 36407216, 2022).
psychosis (1 paper, 2023). "In a previous analysis of data retrieved from 260 subjects with their first episode of psychosis, it was shown that GLP-1 and glucagon levels were significantly decreased in the whole sample of patients, representing the metabolism regulators mostly altered in the whole cohort." (PMID 36979648, 2023).
Salmonella Infections (1 paper, 2023). Infections with bacteria of the genus SALMONELLA. "These were mostly enriched in “Ribosome”, “Coronavirus disease”, “Ferroptosis”, “Glycolysis/Gluconeogenesis”, “Salmonella infection”, “Gap junction”, “GnRH signaling pathway”, “AGE-RAGE signaling pathway in diabetic complications”, “Longevity regulating pathway” and “Glucagon signaling pathway”." (PMID 37047552, 2023).
skin aging (1 paper, 2023). The gradual irreversible changes in structure of skin that occur as a result of the passage of time.. "Results showed that 39 circadian rhythm-related genes (CRGs) were identified in skin aging, and these CRGs were enriched in signaling pathways such as glucagon signaling pathway, insulin resistance, thyroid hormone signaling pathway, and adipocytokine signaling pathway." (PMID 37905958, 2023).
Skin rash (1 paper, 2011). A red eruption of the skin. "Normalization of glucagon concentrations by surgery results in a rapid disappearance of the skin rash." (PMID 21859461, 2011).
Strongyloides infection (1 paper, 2023). "In a second study, individuals with T2DM and Strongyloides infection had similar hemoglobin A1c and random blood glucose levels, but lower insulin and glucagon levels, compared to uninfected individuals with T2DM at baseline." (PMID 36827239, 2023).
substance abuse (1 paper, 2024). The use of a drug for a reason other than which it was intended or in a manner or in quantities other than directed. "A detailed analysis of pathophysiological aspects, encompassing hemodynamics, electrolyte disturbances, serum glucagon alterations, and the impact of alcohol and substance abuse during hot tub use, was conducted." (PMID 38496149, 2024).
Thrombocytopenia (1 paper, 2020). A reduction in the number of circulating thrombocytes. "In this patient cohort, no cases of thrombocytopaenia secondary to glucagon treatment were reported." (PMID 33013678, 2020). "While the incidence of AEs from glucagon use was infrequent (1 other child had diarrhea, while none had thrombocytopenia), it is important to be aware of the possibility of AEs from longer-term use of glucagon infusion therapy." (PMID 33013678, 2020).
VLCAD deficiency (1 paper, 2023). "In conclusion, the fasting glucagon concentrations are lowered in patients with VLCAD deficiency, and this is likely driven by the defect of FAO in itself rather than altered factors in the plasma." (PMID 37512487, 2023).
Zinc deficiency (1 paper, 2021). A deficiency of the essential metal Zinc; an essential cofactor for many enzymes. "In this study, zinc deficiency is a significant risk factor for exocrine and endocrine pancreatic dysfunction as zinc is involved in many of these processes within the pancreas, including glucagon secretion, digestive enzyme activity, and insulin packaging, secretion, and signaling." (PMID 34686155, 2021).
cancer (145 papers, 2010 to 2026). A tumor composed of atypical neoplastic, often pleomorphic cells that invade other tissues. "Meanwhile, in this study, we observed a distinct distribution of serum metabolites in OSs compared to HCs, which was associated with carbon metabolism in cancer, the glucagon signaling pathway, and the citrate cycle (TCA cycle) pathways." (PMID 40746321, 2025). "Taken together, our results demonstrate that malignant tumors cause organ wasting via elevation of glucagon production." (PMID 39924534, 2025). "The data on GCG expression further complicate this picture, showing both protective and harmful associations with cancer survival, depending on the cancer type." (PMID 39777709, 2025). "Notably, SLC2A1, which encodes the major glucose transporter 1 (GLUT1) The Cancer Genome Atlas (TCGA) and plays a crucial role in the glycolytic pathway, was enriched in the Glucagon signaling pathway." (PMID 40278414, 2025). "Blockade of either glucagon or PDGFR (homolog of Pvr) action efficiently ameliorated organ wasting in the presence of malignant tumors." (PMID 39924534, 2025). "This study used pNETs as a cancer model to explore how glucagon and glucose affect cancer cell metabolism and malignancy." (PMID 40649254, 2025). "These pathways include glyoxylate and dicarboxylate metabolism, the citrate cycle (TCA cycle), the glucagon signaling pathway, central carbon metabolism in cancer, and ascorbate and aldarate metabolism." (PMID 39933005, 2025). "The role of glucagon as a cancer regulator, and the usefulness of the GCGR and GLP1-R as biomarkers are underexplored." (PMID 40649254, 2025). "This study presents a comprehensive analysis of the relationship between GLP1R and GCG expression and overall survival across various cancer types." (PMID 39777709, 2025). "Although insulin’s impact has been addressed in different cancer models, the impact of glucagon and hyperglucagonemia (>100 pmol/mL) on the TME and consequent effect on cancer metabolic remodelling is not well understood." (PMID 40649254, 2025). "Of note, half of the top six pathways pertained to carbon metabolism in cancer, glucagon signaling pathway, and citrate cycle (TCA cycle) were closely linked to carbohydrate metabolism." (PMID 40746321, 2025). "The expression of the GCGR in pNET cell lines and the effects of glucagon on pNET and non-cancer cells were investigated." (PMID 40649254, 2025). "These metabolites were correlated with cancer’s carbon metabolism, glucagon signaling, and the citrate cycle pathways." (PMID 40746321, 2025). "KEGG enrichment analysis highlights the top five most significantly enriched metabolic pathways: glycerophospholipid metabolism, choline metabolism in cancer, glucagon signaling pathway, glycolysis/gluconeogenesis, and central carbon metabolism in cancer." (PMID 39588104, 2024). "Although glucagon has demonstrated antiangiogenic potential, this requires further validation in different cancers or chemotherapeutic drug treatments." (PMID 38072640, 2024). "In the plerocercoid stage, glycolysis/gluconeogenesis, proteoglycans in cancer, tight junctions, the glucagon signaling pathway, and the insulin signaling pathway were the most highly enriched KEGG pathways." (PMID 39217359, 2024). "The remaining five enriched pathways included central carbon metabolism in cancer, mineral absorption, the glucagon signaling pathway, protein digestion and absorption, and aminoacyl-tRNA biosynthesis." (PMID 37623844, 2023). "Glucose and glucagon are critical in cancer-cell metabolism, and their uptake by cancer cells is enhanced through oncogenic signaling." (PMID 36077845, 2022). "The expression pattern and prognostic significance of GCG gene in pan-cancer and TCGA-COADREAD data were investigated by performing unpaired and paired sample analyses." (PMID 35340411, 2022).
cancer (continued). "KEGG pathway analysis showed that genes in the module were enriched in glycolysis/gluconeogenesis, HIF-1 signaling pathway, central carbon metabolism in cancer, and glucagon signaling pathway." (PMID 36212136, 2022). "The highly upregulated PYGM gene, an enzyme involved in glycogenolysis, is involved in diverse insulin and glucagon signaling, necroptosis, inflammatory response, cellular energy support, and cancer progression." (PMID 35741360, 2022). "According to the KEGG pathway analysis results, the differentially expressed mRNAs were primarily abundant in the MAPK signaling pathway, central carbon metabolism in cancer, the glucagon signaling pathway, glutamatergic synapse, and spliceosome." (PMID 35573701, 2022). "The cytoplasmic C-terminal domain of PROM1 binds to PI3K and radixin, maintaining cancer stem cell properties and regulating glucagon-induced PKA activity, respectively." (PMID 36266314, 2022). "According to the KEGG pathway analysis results, the differentially expressed proteins were primarily enriched in the MAPK signaling network, central carbon metabolism in cancer, the glucagon signaling pathway, glutamatergic synapse, and spliceosome." (PMID 35573701, 2022). "For the KEGG analysis, metabolic pathways, such as “central carbon metabolism in cancer,” “glycolysis/gluconeogenesis,” “glucagon signaling pathway,” “oxidative phosphorylation,” and “thermogenesis” were enriched by these lncRNAs." (PMID 34249094, 2021). "KEGG pathway analysis revealed the Top 5 enriched signaling pathways involved in the progression of MCAO, including pathways in cancer, lysosome, long-term potentiation, phosphatidylinositol signaling system, and glucagon signaling pathway." (PMID 33408783, 2021). "Glucocorticoids, adrenaline, and glucagon are stress hormones that induce increased hepatic synthesis of glucose, a key substrate of cancer and brain cells." (PMID 32426290, 2020). "Molecular assays showed that glucagon acted as an activator of cancer cell growth through deactivation of AMPK and activation of MAPK in a GCGR-dependent manner." (PMID 29535833, 2018). "Pathways in cancer, focal adhesion, and glucagon signaling categories were the main metabolic pathways for both PL10 vs. PL13, and PL10 vs. PL16." (PMID 28931848, 2017). "In total, 5 vital sex-related metabolic pathways were identified based on the GO and KEGG analysis of DEGs, including Biosynthesis of amino acids, Pathway in cancer, Focal adhesion, Glucagon signaling categories, and Ubiquitin proteolytic system." (PMID 28931848, 2017). "Kyoto Encyclopedia of Genes and Genomes (KEGG) enrichment analysis revealed that the cGMP-PKG signaling pathway, glucagon signaling pathway, central carbon metabolism in cancer, and lipolysis regulation in adipocytes are metabolic pathways significantly associated with unstable plaques." (PMID 42205783, 2026). "However, the KS vs. KC group displayed an additional increase in the central carbon metabolism in cancer pathway, while the KS vs. WC group exhibited an increase in the glucagon-signaling pathway." (PMID 39997759, 2025). "Therefore, the role of glucagon in human glucose homeostasis is unveiled, although at the cellular level, especially in cancer cells, much information is yet to be explored." (PMID 40649254, 2025). "Additionally, ectopic c‐Fos expression was associated with upregulation of genes in PI3K‐Akt signaling, Ras signaling, proteoglycans in cancer, estrogen signaling, and glucagon signaling." (PMID 41024433, 2025). "The effect of insulin has been rather exploited in cancer, but glucagon has been passed over." (PMID 40649254, 2025). "Consequently, the role of glucagon in cancer cell survival and tumour progression is underexplored, despite its potential as a regulator of cellular metabolism in predominant organ systems." (PMID 40649254, 2025). "This discovery suggests glucagon maybe developed as an endogenous antiangiogenic inhibitor for cancer therapy." (PMID 38072640, 2024).
cancer (continued). "This study aimed to elucidate a novel role of glucagon in anti‐cancer therapy." (PMID 38072640, 2024). "In addition, data from the cancer genome atlas program (TCGA) showed a 5‐year survival rate of 74% for patients with high glucagon levels, compared to only 47% for those with low glucagon expression." (PMID 38072640, 2024). "The most enriched pathway of differential metabolites between the Post‐Male group and Pre‐Male group is central carbon metabolism in cancer, biosynthesis of amino acids and glucagon signaling pathway, all of them are closely related to energy recovery after exercise." (PMID 39352112, 2024). "Additionally, glycolysis/gluconeogenesis, central carbon metabolism in cancer, biosynthesis of amino acids, and the glucagon signaling pathway were also enriched, reflecting the multifaceted adaptations occurring in cells subjected to prolonged hypoxia." (PMID 39050708, 2024). "The delivery of glucagon to patients with cancer may be a potential approach to increase chemotherapy efficacy." (PMID 38072640, 2024). "The KEGG enrichment analysis showed pathways, including TCA, Glycolysis/Gluconeogenesis, pyruvate, and carbon metabolism, as well as central carbon metabolism in cancer, resistance to platinum drugs, and the glucagon and HIF-1 signaling pathways were enriched by these CRGs." (PMID 38062233, 2023). "Simultaneously, we performed KEGG function enrichment and identified that these different metabolites are closely related to these pathways, such as central carbon metabolism in cancer, glucagon signaling pathway, glyoxylate, dicarboxylate metabolism, and TCA cycle." (PMID 38086844, 2023). "These systemic effects are very relevant for cancer therapy, as glucagon can have anti-tumor effects through unknown mechanisms." (PMID 37202813, 2023). "None of fasting glucose, insulin and glucagon showed significant associations with incident first cancer in the sensitivity analyses." (PMID 36611045, 2023). "Based on this analysis, the proteins that are produced from mRNAs that are targeted by the miRNAs participate most frequently in metabolic pathways and pathways in cancer, such as the calcium signaling pathway, cAMP signaling pathway, and glucagon signaling pathway." (PMID 35885916, 2022). "Furthermore, KEGG pathway analysis revealed the involvement of the TCA cycle, pyruvate metabolism, gluconeogenesis, carbon metabolism, HIF-1 signaling pathway, miRNAs in cancer, and glucagon signaling pathway." (PMID 36312586, 2022). "In addition, these genes were highly enriched in the HIF-1 signaling pathway, glucagon signaling pathway, and central carbon metabolism in cancer." (PMID 36387247, 2022). "Furthermore, the enriched KEGG pathways of up-regulated DEGs included transcriptional misregulation in cancer, viral carcinogenesis, and glucagon signaling pathway." (PMID 34017995, 2021). "Finally, four pathways, namely galactose metabolism, adherens junction, central carbon metabolism in cancer and glucagon signaling pathways, were identified to be common at established and end-stage disease stages." (PMID 32552896, 2020). "Moreover, elevated glucagon levels promote hepatic gluconeogenesis, thereby increasing plasma glucose levels in cancer cachexia." (PMID 32850383, 2020). "Also, our functional enrichment analysis suggested CAMKIIG to regulate the HCSC microenvironment through regulation of Proteoglycans in cancer, Neurotrophin signaling pathways, Glucagon signaling pathway and Oocyte meiosis pathway." (PMID 30944375, 2019). "Moreover, PA increases glucagon, catecholamines, and other hormones and influences miRNAs involved in cancer." (PMID 30363988, 2018). "Consequently, the specific role of EEF1A2 in cancers derived from glucagon-producing pancreatic islet cells remains unclear." (PMID 38172654, 2024). "Therefore, it is important to clarify the role of glucagon in cancer development." (PMID 38072640, 2024).